FNDC5 (fibronectin type III domain containing 5)
Diseases named in the same sentence as FNDC5 in open-access papers (continued):
Sharing a sentence is not in itself a finding about the gene and the disease.
metabolic disease (22 papers, 2014 to 2025). A congenital disorder (due to inherited enzyme abnormality) or acquired (due to failure of a metabolically important organ) disorder resulting from an abnormal metabolic process. "Irisin, an exercise-stimulating cleaved product from transmembrane fibronectin type III domain-containing protein 5 (FNDC5), has been linked with favorable effects on many metabolic diseases." (PMID 35431908, 2022). "Multiple SNPs significantly associated with metabolic disease susceptibility in different populations have been found in the FNDC5 gene." (PMID 36004352, 2022). "According to the role of irisin in browning of white adipose tissue and its possible function in reducing insulin resistance, several researchers have assessed the degree of FNDC5 expression in different tissues in pathogenic states related to metabolic disorders including PCOS." (PMID 30009142, 2018). "Several investigations have focused on FNDC5/irisin levels in the context of pathological conditions, especially metabolic disorders with mixed outcomes." (PMID 40427436, 2025). "Although the roles of FNDC5/irisin in metabolic disorders have been documented, it is widely thought that these proteins have various functions in the central nervous system (CNS)." (PMID 38802337, 2024). "In this respect, exercise-induced activation of the AMPK–SIRT1–PGC-1α–FNDC5/Irisin–UCP1 axis can be an attractive therapeutic target for ameliorating metabolic diseases." (PMID 37041517, 2023). "FNDC5/irisin is a promising intervention target in the treatment of metabolic disease based on its role in browning white adipocyte tissue." (PMID 32933582, 2020). "Muscle expression of the FNDC5 gene was 200-fold higher than that of adipocytes, indicating a relationship between muscle and adipose tissue functions in metabolic diseases." (PMID 30477139, 2018). "Elucidation of the FNDC5 gene regulation mechanism is necessary to clarify the function of irisin as a potential therapeutic target in human metabolic diseases." (PMID 28240298, 2017). "Previous studies have shown that miR-135-5p preferentially binds to the G allele of rs3480 after upregulation, thus enhancing the attenuating effect of miR-135-5p on FNDC5 and reducing the FNDC5 mRNA levels, which results in a weakened regulatory effect of FNDC5 on metabolic diseases." (PMID 36004352, 2022). "FNDC5/Irisin is a recently identified exercise-induced myokine, which improves systemic metabolism via increasing energy expenditure and serves as an appealing therapeutic target for treatment of metabolic disorders." (PMID 31209361, 2020). "FNDC5/Irisin was traditionally found in muscle and regarded as a myokine that drives brown-fat-like development of white fat and thermogenesis, which was suggested as a therapeutic agent for human metabolic diseases." (PMID 31209361, 2020). "Given the lack of data implicating FNDC5 variants in human metabolic disease, we set out to examine the association between FNDC5 variants and a range of metabolic parameters in a large Chinese Han population." (PMID 25369206, 2014). "Therefore, FNDC5 is considered an attractive target for metabolic disease." (PMID 36004352, 2022). "Since metabolic disorders are multifactorial diseases and are affected by a number of factors such as ethnicity, social and environmental factors such as climate, diet and life style, this study aimed to evaluate the expression of PGC1α, which is a transcription factor upstream of FNDC5." (PMID 30009142, 2018). "It is suggested that glucose and lipid, not insulin might be inhibitory regulatory factor in muscle FNDC5 expression in metabolic disorders." (PMID 27354972, 2015).
cancer (21 papers, 2017 to 2025). A tumor composed of atypical neoplastic, often pleomorphic cells that invade other tissues. "In turn, an increased level of FNDC5/Ir expression in cancer-associated fibroblasts (CAFs) in patients with NSCLC was a negative prognostic factor." (PMID 37239973, 2023). "We supposed that the higher FNDC5 mRNA level was associated with the interaction between healthy margin cells and cancer cells." (PMID 35408891, 2022). "Understanding the precise underlying mechanisms of Fndc5 is required to fully appreciate and appropriately apply Fndc5/irisin in cancer, aging and other metabolic diseases." (PMID 32257109, 2020). "In cancer, FNDC5 inhibits the transcription of the gene encoding E-cadherin and participates in the expression of the epithelial-mesenchymal transition (EMT) transcription factor Snail, which consequently inhibits migration, proliferation, and invasion in vitro." (PMID 40313961, 2025). "The increased expression level of mRNA encoding FNDC5 in BC cells may be related to the metabolic changes occurring in the cancer cells." (PMID 35408891, 2022). "Previous studies indicated that DOX application significantly decreased the body weight in cancer patients, but intriguingly, we found that cardiac-specific overexpression of FNDC5 attenuated DOX-induced body weight loss in mice, which raises the possibility for its clinical use." (PMID 31209361, 2020). "Expressions of FNDC5 variants were diverse in different types of normal and cancer cell lines." (PMID 28240298, 2017). "The expression patterns of FNDC5 variants were diverse in the normal and cancer cell lines." (PMID 28240298, 2017). "FNDC5 levels in tumors were lower than those in neighboring normal tissues, as demonstrated by 8 analyses involving 3 different types of cancer; only 1 analysis revealed an increased level." (PMID 36626432, 2022). "FNDC5 gene expression was measured in 40 BC tissue samples, 40 samples from the cancer margin, and 16 NMBD samples." (PMID 35408891, 2022). "In our previous study, we found that the expression of FNDC5 was higher in cancer than in normal tissues." (PMID 35392237, 2022). "It was shown that the expression of FNDC5 mRNA from NSCLC tissues in stromal cells was higher than that in cancer cells." (PMID 34204674, 2021). "The expression of the FNDC5 gene was significantly higher in cancer cells compared to normal lung tissue." (PMID 31614634, 2019). "The expression level of the FNDC5 gene was higher in NSCLC stromal cells in comparison to NSCLC cancer cells and normal lung cells (mean 1.2 ± 0.3)." (PMID 31614634, 2019). "Among the comorbidity genes of OC and CC, FNDC5 may play a tumor-suppressive role in both cancers, primarily mediated through the PI3K/AKT signaling pathway." (PMID 41231350, 2025). "The increased level of FNDC5/Ir expression in cancer cells may result from the increasing energy demand of the cancer cell and the modification of its metabolic processes." (PMID 37239973, 2023). "FNDC5/Irisin has been shown to aid the diagnosis for several cancers." (PMID 36386179, 2022). "Serum irisin protein was increased in gastric cancer and increased FNDC5 expression may have a cachexia effect in cancer-induced mice." (PMID 36386179, 2022). "The analysis of the results of FNDC5 gene expression in normal fibroblasts after incubation with cancer cells may indicate that cancer cells could influence the alteration of gene expression levels in stromal cells and change their metabolism." (PMID 36430689, 2022). "Cancer development corresponded to an increase in FNDC5 expression in the adipose tissue." (PMID 34204674, 2021). "The mechanism of the relationship between cancer and the increase in FNDC5 mRNA expression in the adipose tissue and the increase in serum Ir levels is unknown." (PMID 34204674, 2021). "We noticed a higher FNDC5 gene expression in NSCLC stromal cells in comparison to cancer cells." (PMID 31614634, 2019).
cancer (continued). "Thus, FNDC5 has cooperative effects with GADD45B on prognosis of cancer patients." (PMID 37746289, 2023). "In addition, lower FNDC5 mRNA levels were observed in the group of patients with N1 cancer." (PMID 35408891, 2022). "Irisin (Ir) is an adipomyokine formed from fibronectin type III domain-containing protein 5 (FNDC5), which can be found in various cancer tissues." (PMID 37239973, 2023). "In our previous study, we found that FNDC5 was highly expressed in HCC tissues, promoting cancer progression." (PMID 35392237, 2022). "Irisin is a myokine formed from fibronectin type III domain-containing protein 5 (FNDC5), which can be found in various cancer tissues." (PMID 35408891, 2022). "Laser Capture Microdissection and RT-PCR, which were used to determine the FNDC5 mRNA expression levels in NSCLC stromal and cancer cells, confirmed the TMA IHC observations." (PMID 31614634, 2019). "As the role of FNDC5 has also been gradually revealed in tumors and in the progression of HCC, FNDC5 has been suggested to play a role in promoting the proliferation of cancer cells." (PMID 35392237, 2022). "Oncomine revealed that the mRNA expression levels of FNDC1, FNDC3A, and FNDC3B were higher in most malignancies than in normal tissues, but the mRNA expression levels of FNDC4, FNDC5, FNDC7, and FNDC8 were downregulated in most cancers when compared with normal tissues." (PMID 36626432, 2022). "However, more research is needed to determine the functional relationship between these proteins and to confirm their involvement in the control of FNDC5 gene expression in NSCLC, as well as potentially other types of cancer." (PMID 36430689, 2022). "For FNDC5, cancer tissues were not significantly different from the normal tissues." (PMID 36626432, 2022).
tumor (19 papers, 2017 to 2025). "In our previous paper, we observed an association of FNDC5/irisin expression with the histological malignancy grade, tumor size, and lymph node metastases in non-small cell lung carcinoma (NSCLC)." (PMID 35408891, 2022). "However, further studies are warranted to explain the cause of such a high level of FNDC5 mRNA in the tissue from the surgical margin surrounding the tumor." (PMID 35408891, 2022). "The search terms included ‘irisin’ or ‘Fndc5’ with ‘cancer’, ‘tumour’, ‘neoplasia’, ‘oncogenesis’, ‘cell proliferation’, ‘apoptosis’, ‘metastasis’, ‘epithelial-mesenchymal transition (EMT)’, ‘IGF-1’, and ‘PI3K/Akt/mTOR pathway’." (PMID 41002741, 2025). "To further assess the potential function of FNDC5 in tumor T and M stages, we incorporated in vitro experiments." (PMID 40313961, 2025). "For each protein, we analyzed the correlation of its expression level with the level of FNDC5/Ir in tumor cells." (PMID 37239973, 2023). "Ultrastructural studies showed the presence of FNDC5/Ir in the cytoplasmic structures of BC tumor cells and stromal fibroblasts." (PMID 37239973, 2023). "The mRNA expression of BDNF, IL15, and MSTN were significantly higher in tumor tissues than in paraneoplastic tissues, while the expression of FNDC5 was significantly reduced in tumor tissues." (PMID 36733390, 2022). "The expression level of the FNDC5 gene in BC was analyzed compared to the control samples (tissues from tumor margins and NMBD samples)." (PMID 35408891, 2022). "Due to the effect of the transcription factor PGC-1α on FNDC5 gene expression, we analyzed its correlation with irisin levels in tumor cells." (PMID 35408891, 2022). "Numerous studies have demonstrated that FNDC5 exerts differential effects on tumor cell proliferation and apoptosis in breast, lung, and liver cancer through multiple mechanisms." (PMID 36386179, 2022). "The expression levels of BDNF, IL15, and MSTN were significantly higher in tumor tissues than in paraneoplastic tissues, while the expression level of FNDC5 was significantly reduced in tumor tissues." (PMID 36733390, 2022). "RT-PCR revealed a higher expression of FNDC5 mRNA in tissues of NSCLC tumours (mean 31.36 ± 5.6) than in NMLTs (mean 3.6 ± 0.3) (Mann-Whitney U, p < 0.0001)." (PMID 31614634, 2019). "Additionally, FNDC5 was related to tumor T stage and M stage, suggesting a potential role in COAD metastasis." (PMID 40313961, 2025). "Additionally, the ways in which FNDC5 impacts tumor metastasis in the TME have yet to be thoroughly explained." (PMID 40313961, 2025). "Therefore, function of FNDC5 in enhancing HCC progression is based on triggering M2 polarization of macrophages and if the interaction of FNDC5 with other pathways is suppressed, it can lead to M1 polarization and reduced progression of tumor cells." (PMID 38997297, 2024). "FNDC5/Ir was present in BC cell cytoplasm and tumor fibroblasts." (PMID 37239973, 2023). "Next, we evaluated whether FNDC5 affected the tumor microenvironment and the effect on immune cells infiltrating inside the tumor." (PMID 36386179, 2022). "In addition, compared to BC and NMBD samples, the higher FNDC5 mRNA levels observed in normal tissue from the tumor margin are interesting." (PMID 35408891, 2022). "However, FNDC5 gene expression in the NMBD samples was significantly lower than that in the tumor margin tissue (Mann–Whitney U test p < 0.0001)." (PMID 35408891, 2022). "FNDC5 plays an important role in the occurrence, development, and metastasis of different tumors, suggesting that FNDC5 may serve as a potential target for tumor diagnosis and therapy." (PMID 36386179, 2022). "Furthermore, several in vitro studies described FNDC5/irisin as a myokine with diverse anti-tumour activities in various cancer cells." (PMID 34359731, 2021).
tumor (continued). "Recent data also supported the role of FNDC5/irisin in alleviating oxidative stress caused by doxorubicin-induced cardiac toxicity in an AKT/mTOR-dependent pathway, with improved the sensitivity of the tumor response to chemotherapy." (PMID 34899376, 2021). "It was also found that, in patients with HCC and tumor-enhanced lipogenesis, increased paracrine production of FNDC5/Ir could compensatively inhibit lipid synthesis." (PMID 34204674, 2021). "We also found that the FNDC5 expressions were different among tissues and matched non-tumor cell lines of heart (AC16) and liver (MIHA), which might be due to transcriptional remodeling during immortalization and adaptation of cells in in vitro environments." (PMID 28240298, 2017). "Additionally, FNDC5 is a tumor regulator that affects tumor-proliferation and -invasion abilities." (PMID 36056336, 2022). "We investigated the association of FNDC5 with various immune cells in the tumor microenvironment and found a significant negative correlation between FNDC5 and CD4+ memory T cells, implying an increase in the number of CD4+ memory T cells when FNDC5 was lowly expressed." (PMID 36386179, 2022). "FNDC5 has been considered as an oncogenic factor and upregulation of FNDC5 can result in epithelial–mesenchymal transition (EMT) in enhancing tumor invasion." (PMID 38997297, 2024). "Then, we examined the mRNA expression levels of BDNF, FNDC5, IL15, and MSTN, in tumor tissues and paracancerous tissues." (PMID 36733390, 2022). "We found that four muscle failure-related genes (BDNF, FNDC5, IL15, MSTN) were significantly increased in tumor cells." (PMID 36733390, 2022). "We examined the mRNA expression of four myokine/exerkine genes, BDNF, FNDC5, IL15, and MSTN, in tumor and paraneoplastic tissues." (PMID 36733390, 2022). "Myokines, such as IL-6, irisin/FNDC5, decorin, oncostatin M (OSM), and secreted protein acidic and rich in cysteine (SPARC), have shown the potential of a direct tumor-suppressive effect in different cancer cell lines, including PCa." (PMID 34595123, 2021). "Studies have shown that exercise can stimulate the production of irisin by inducing FNDC5, which then mediates autophagy through the AMPK-ULK1 signaling pathway, inhibits NF-kB activation, and exerts anti-inflammatory effects that interfere with tumor progression." (PMID 40704062, 2025).
neurodegenerative disease (6 papers, 2021 to 2025). A disorder of the central nervous system characterized by gradual and progressive loss of neural tissue and neurologic function. "Therefore, FNDC5 seems to correspond to a multifunctional protein with therapeutic potential in metabolic and neurodegenerative diseases, although many aspects of its molecular and physiological biology still require further understanding." (PMID 40648864, 2025). "However, this is an interesting topic because patients with ALS are characterized by muscle damage, and FNDC5/irisin, known for its anabolic action on skeletal muscle, could represent a biomarker of muscle damage in neurodegenerative diseases." (PMID 33562601, 2021). "When the levels of CaMkII and AMPK are reduced at the onset of neurodegenerative disease, the consequent reduced ability to express PGC-1α, FNDC5, BDNF, NGF, and GDNF could lead to cognitive dysfunction and deteriorating physical fitness." (PMID 35805580, 2022).
cardiovascular diseases (4 papers, 2019 to 2025). "Notably, FNDC5 expression decreases with aging, and the FNDC5 gene was shown to be critical for exercise benefits in attenuating various age-associated pathologies, including cardiovascular diseases." (PMID 40001564, 2025). "This review discusses the current knowledge about the role of FNDC5/Ir in cardiovascular disease." (PMID 38334669, 2024). "Therefore, the levels of FNDC5/Ir in the blood and myocardium may be important in cardiovascular disease." (PMID 38334669, 2024).
heart disease (3 papers, 2020 to 2025). "In another study, the FNDC5/irisin pathway has been demonstrated to enhance cardiac function and aerobic fitness in mice with radiation-induced heart disease." (PMID 40725790, 2025). "Irisin as a cleaved product of fibronectin type III domain‐containing protein 5 (FNDC5) displays cardioprotection in diverse cardiac diseases." (PMID 32997406, 2020).
inflammation (3 papers, 2016 to 2022). Aberrant reaction of the microcirculation characterized by movement of fluid and leukocytes from the blood into extravascular tissues. "Phospho-JAK2/STAT3 level were downregulated in FNDC5 OE mice, suggesting that the protective role of FNDC5 in cardiac inflammation are associated with JAK2/STAT3 pathway inhibition." (PMID 30940158, 2019). "Recent studies have revealed that FNDC5 protects cells from oxidative damage in myocardial inflammation and neurological diseases and reduces the production of ROS, inhibiting the occurrence of ferroptosis in cells." (PMID 35392237, 2022). "To investigate whether the inflammation-induced regulation of Fndc4 in mice translates to humans, we analysed FNDC4 and FNDC5 expression in patients with IBD and controls without intestinal inflammation." (PMID 27066907, 2016).
myopathy (3 papers, 2020 to 2023). A disease of the muscle in which the muscle fibers do not function properly. "Future studies will be needed to understand the mechanisms underlying exacerbated FNDC5 cleavage and muscle irisin resistance in these inflammatory myopathies." (PMID 36768791, 2023). "Exercise upregulates FNDC5/irisin expression via PGC1a, enhances mitochondrial fission and mitophagy, and improves myopathy following critical limb ischemia in aged mice." (PMID 35805170, 2022).
brain disorder (2 papers, 2020 to 2023). A disease affecting the brain or part of the brain. "Hippocampal Fndc5/irisin signaling might be a promising therapeutic target for treating the brain disorders associated with CCH." (PMID 36823656, 2023).
infection (2 papers, 2019 to 2023). The state of being infected such as from the introduction of a foreign agent such as serum, vaccine, antigenic substance or organism. "As expected, FNDC5 was induced at all times from PGC1α infection (but not after PGC1β), although much less than all the other genes that were PGC1α targets in our screening." (PMID 31614775, 2019).
neurological diseases (2 papers, 2021 to 2022). "PGC‐1α/FNDC5/BDNF pathway is one of them whose importance in neuroprotection as an effective target in neurological diseases and ageing has been highlighted." (PMID 34018309, 2021).
blood cancers (1 paper, 2022). "Moreover, the expression of FNDC3A, FNDC3B, FNDC5, and FNDC6 has been implicated in the prognosis of blood cancers." (PMID 36626432, 2022).